IL15 (interleukin 15)
Diseases named in the same sentence as IL15 in open-access papers (continued):
Sharing a sentence is not in itself a finding about the gene and the disease.
tumor (continued). "Upon stimulation with tumor cells, specific degranulation of IL‐15‐preactivated NK cells was two‐ to threefold higher (21–34%) than that of IL‐12/15/18‐preactivated NK cells (9–11%)." (PMID 25778912, 2015). "IL-15 has been administered by several routes and use of each of these methods has impaired tumor growth or metastasis." (PMID 25879689, 2015). "Instead, the tumor environment in IL-15−/− mice, with reduced selective pressure of cellular cytotoxicity, revealed an unexpected transcriptional profile in the malignant cells that is apparently masked by tumor immunity." (PMID 24416335, 2014). "In conclusion, tumor-induced and IL-15-supported murine NK cell activation appears to be limited to a subset of early NK cells." (PMID 25101668, 2014). "The therapeutic antitumor efficacy of these IL-15-based strategies has been demonstrated in transplantable tumor models." (PMID 25941586, 2014). "It was recently reported that IL-15 stimulation resulted in a significant enhancement of CIK cell-mediated cytotoxicity against tumor cells compared to IL-2-induced CIK cells." (PMID 24748966, 2014). "IL-15 expression is known to be elevated in these tumors but the role of IL-15 and its effect on the tumor is unclear." (PMID 24416335, 2014). "Our previous study have shown that CIK cells stimulated with combination of IL-2 and IL-15 displayed improved proliferation capacity and tumor cytotoxicity." (PMID 25108500, 2014). "We have designed a novel DCIL-15-based cancer vaccine platform in which DC specifically express human IL-15 transgene and simultaneously produce tumor Aghsp70, and demonstrated its efficacy in effectively inducing prophylactic antitumor immunity." (PMID 25941586, 2014). "In contrast, when the peripheral-derived γδ T cells were cultured with irradiated autologous tumor cells in the presence of IL-2 and IL-15, they showed markedly increased proliferation (defined as tumor-activated γδ T cells) (n = 9, P < 0.01)." (PMID 24741609, 2014). "IL-15 has proliferative effects on NK cells, effector CD8+, and memory phenotype CD8+ T cells, and a clinical trial based on application of IL-15 in tumor patients has begun." (PMID 28548063, 2014). "Accordingly, ex vivo-generated DC or tumor cells co-expressing transgene IL-15 and IL-15Rα, and engineered IL-15 agonists (e.g., IL-15/IL-15Rα-Fc complex, IL-15/IL-15Rα fusion protein) have been explored to generate effective antitumor responses." (PMID 25941586, 2014). "Previous studies have done depletion of NK cells prior to treatment to show that NK cells contribute to the anti-tumor effect of IL15/IL15Rα." (PMID 25329832, 2014). "Although IL-15 is regarded as an excellent candidate for tumor therapy, it has also been characterized as a promoter of cancer." (PMID 24416335, 2014). "Interleukin-15 (IL15) is an immuno-modulatory cytokine with significant potential for stimulating anti-tumor T lymphocytes and NK cells." (PMID 25329832, 2014). "This study further confirmed the requirement for the combination of IL-2 or IL-15 with anti-CD40 mAb for tumor regression versus the partial effects seen with anti-CD40 mAb treatment alone in large tumor burdens." (PMID 24955376, 2014). "The increase in tumor growth was transiently reversed in the presence of soluble IL-15 and the dearth of NK and CD8+ T cells in IL-15−/− mice is the likely cause of this phenotype." (PMID 24416335, 2014). "In combination with other interleukins, such as IL-12 and IL-15, IL-18 can be used to pre-activate NK cells with anti-tumour functions." (PMID 24778454, 2014). "The potential mechanisms by which IL-15 mediates its pro-tumor activity include protecting tumor cells from apoptosis, and promoting proliferation, migration, invasion and metastasis." (PMID 24416335, 2014). "Studies from the Cerwenka lab demonstrated that a single infusion of IL-12, IL-15, and IL-18 preactivated NK cells protected against established tumor cell line implant (B16 melanoma and RMA-S lymphoma)." (PMID 25054077, 2014).
tumor (continued). "IL-15 is recognized as a promising candidate for tumor immunotherapy and has been described as both a promoter of cancer and a promoter of anti-cancer immunity." (PMID 24416335, 2014). "Specifically, tumor (5 mm)-bearing animals treated with E7 DNA vaccines plus IL-2 cDNA displayed a 50% tumor cure rate, whereas animals treated with E7 DNA vaccines alone or E7 DNA vaccines plus IL-15 cDNA showed 0% and 33% tumor cure rates, respectively." (PMID 24391824, 2013). "The anti-tumor effects of IL-15 have been documented following systemic administration of IL-15 in complex with soluble IL-15Rα, as well as engineering tumor cells to produce IL-15 alone in the local tumor microenvironment." (PMID 24312353, 2013). "The expression of CD86 on NK cells was significantly increased following activation with both YAC-1 tumor cells (from 6.2% to 12.6%) and cytokine IL-15 in vitro." (PMID 24349559, 2013). "Cytokines that foster activation of lymphocytes such as IL-2 or IL-15 have been evaluated in preclinical models and are currently tested in clinical studies to augment tumor-specific immunity." (PMID 24312302, 2013). "Recent studies in mice have shown that adoptively transferred T cells demonstrated superior in vivo persistence and tumor elimination when pre-treated with either IL-15 or IL-21." (PMID 23402380, 2013). "The addition of IL-15 to the culture media in vitro during T cell activation or its expression as a transgene in transferred T cells further enhanced the anti-tumor function of the adoptively transferred T cells." (PMID 23418547, 2013). "For instance, targeting IL12 to the tumor microenvironment is critical for inducing tumor-specific T cell immune responses, and using antibodies specific for the tumor antigen L19 can increase the antitumor efficacy of IL15." (PMID 24369443, 2013). "Preclinical studies in multiple tumor models have demonstrated therapeutic administration of IL-15 can reduce tumor burden and lengthen survival of tumor bearing animals." (PMID 24312353, 2013). "For example, in the pmel-1 T cell receptor transgenic mouse model of adoptive T cell transfer, the exogenous administration of both IL-15 and IL-2 improved the anti-tumor response during the 34 days of follow-up." (PMID 23418547, 2013). "Blocking HLA class I on tumor cells and IL-15 stimulated NK cells increased cytotoxicity 3.7- and 2.1-fold when compared with groups using resting NK cells and IgG2A, respectively." (PMID 23626949, 2013). "Toll-like receptor ligands and homeostatic cytokines, like IL-7 and IL-15, have been employed to promote the generation and expansion of tumor-specific T cells." (PMID 23935927, 2013). "We also demonstrate that blocking HLA class I on MB cells and/or IL-15 stimulated NK cells can overcome the inhibitory effect mediated by HLA class I overexpression on tumor cells." (PMID 23626949, 2013). "It is important to note that both IL-2 and IL-15 are highly efficient adjuvants that have been shown to enhance tumor-specific T cell responses." (PMID 24312302, 2013). "In terms of IL-15, adoptive transfer of T cells into a lymphopenic tumor-bearing host (which typically occurs after whole body irradiation) leads to increased IL-15-dependent proliferation, expansion, and CD8+ T-cell effector function." (PMID 23509806, 2013). "An autocrine loop between IL-15 and its receptor has been identified as a mechanism for tumor cell expansion in MM." (PMID 22642622, 2012). "IL-15 given exogenously can enhance immune responses and these properties are exploited in tumor therapy and in vaccination strategies." (PMID 23028916, 2012). "Concerning their cytotoxic activity, we demonstrate that IL-15 DCs are able to induce apoptotic cell death of the human K562 tumor cell line, while sparing tumor antigen-specific T cells." (PMID 23284789, 2012).
tumor (continued). "In a mouse model of metastatic renal cancer, the use of anti-CD40 agonist mAb in combination with IL-2 or IL-15 can mediate tumor regression by inducing an inflammatory milieu that inhibited intratumoral Treg and MDSC activities." (PMID 22778760, 2012). "Exploitation of the growth promoting activities of IL-15 supplementation is currently, after encouraging results in preclinical models, validated in clinical trials for tumor therapy and HIV vaccines." (PMID 23028916, 2012). "In this study, we reveal for the first time that IL-15 DCs, in addition to a robust capacity for tumor antigen presentation, possess tumor cell killing potential." (PMID 23284789, 2012). "One approach is to include lymphokines (GM-CSF, IL-12, IL-15) or include tumour cell expression of membrane bound molecules (CD80, CD86)." (PMID 23046944, 2012). "IL-15 was suggested to be superior and distinct from IL-2 in its potential to generate tumour-specific CTL and NK cell responses." (PMID 22563505, 2012). "In this study, we show that IL-15 DCs, in addition to potent tumor antigen-presenting function, possess tumoricidal potential and thus qualify for the designation of killer DCs." (PMID 23284789, 2012). "Recently, an interleukin-15 expressing oncolytic vesicular stomatitis virus showed increased anti-tumor immune response." (PMID 22563505, 2012). "The pattern of inhibition of NK cell surface receptor expression mediated by tumour cells closely resembled that observed when IL-15 stimulated NK cells were treated with the immunosuppressive cytokine TGF-β." (PMID 21909397, 2011). "We modelled this in vitro by establishing longer-term co-cultures (one to seven days) between tumour cell lines and interleukin (IL)-15 stimulated NK cells from the peripheral blood of healthy donors." (PMID 21909397, 2011). "These promising results make IL-15 DCs a qualified candidate for application in DC-based tumor immunotherapy." (PMID 20021667, 2009). "This was more recently supported by the demonstration that IL-15 DCs are endowed with a superior capacity to induce antigen-specific cellular immune responses in an in vitro melanoma tumor model." (PMID 20021667, 2009). "This is the first research study that used a safe viral vector rAAV2 expressing human IL15 gene for cancer immunotherapy and successfully inhibited tumor cell growth on an animal model." (PMID 19422685, 2009). "IL15 engineered tumor cells or daily administration of IL15 can suppress tumor growth has been demonstrated previously." (PMID 19422685, 2009). "When mice bearing the NK-sensitive syngeneic tumor B16 were treated, the presence of IL-15Rα-IgG1-Fc increased the anti-tumor activity of IL-15." (PMID 19319200, 2009). "Though rAAV2 is a small viral vector and can only carry about 5000 nucleotides gene sequence, human IL15 gene (about 600 nucleotides) can be packaged into rAAV2 vector for tumor treatment." (PMID 19422685, 2009). "CD34-lineage- cells cultured with IL-15 and IL-21 for 4 weeks were assayed for NK activity against NK-sensitive tumour cell targets." (PMID 19712464, 2009). "Previous studies convincingly showed that IL-15 DCs are highly capable of inducing antigen-specific T cell responses in both viral and tumor antigen models." (PMID 20021667, 2009). "T cells rescued by IL-2, IL-15 and IL-21 killed peptide coated target cells and tumor cells more efficiently than T cells cultured with IL-7 or without cytokine supplementation." (PMID 17406677, 2007). "The combination of IL-21 + IL-15 resulted in prolonged tumor regression and survival out to 32 days." (PMID 16772043, 2006). "In both models, IL-2 and IL-15 delayed tumor growth, but only IL-21 resulted in significant prevention of tumor progression and improved survival beyond 50 days from tumor challenge." (PMID 16772043, 2006). "Mice treated with the vaccine plus IL-15 or IL-21 alone all died of tumor within 32 days of treatment." (PMID 16772043, 2006).
tumor (continued). "We examined the effect of interleukin-15 (IL-15) gene transfer into tumour cells on the host's anti-tumour response." (PMID 10424745, 1999). "We analyzed gene expression patterns and performed repetitive tumor killing assays to assess the ability of CAR-T cells expanded with IL-2 + IL-7 + IL-15 compared with IL-2 alone to maintain proliferation and cytotoxic function across multiple rounds of tumor cell exposure." (PMID 41892338, 2026). "In addition to IL-8, other cytokines like IL-15 and IL-18 play pivotal roles in the tumor microenvironment." (PMID 41169398, 2025). "In contrast, IL-15 levels in tumor tissues remained elevated at both 48 and 96 h." (PMID 40532661, 2025). "Key genetic modifications such as capsid engineering (e.g., Ad5/Ad37 fiber swaps), incorporation of immunostimulatory genes like IL-15, or the addition of tumor-targeting promoters (e.g., Ki67, hTERT) enable selective targeting of tumor cells and enhance antitumor immune activity." (PMID 40805247, 2025). "However, systemic IL-15 administration is limited by its short half-life and on-target off-tumor toxicity." (PMID 40532661, 2025). "Moreover, Niz985, an IL-15 super-agonist, was shown to replicate the beneficial effects of exercise on tumor immunity." (PMID 40948749, 2025). "Additionally, IL-7 and IL-21 promote T cell persistence and memory formation, whereas the co-expression of IL-21 and IL-15 has proven effective at controlling tumor growth in hepatocellular carcinoma models." (PMID 40771804, 2025). "NK cells rely on JAK-STAT-mediated responses to cytokines such as interleukin-15 (IL-15) for their activation, and the disruption of this signaling could attenuate their tumor surveillance capabilities." (PMID 40507276, 2025). "Furthermore, we show that intratumoral injection of IL-15 complexes traffics to the tumor-draining lymph node, as evidenced by Light sheet microscopy, and colocalizes with the anti-PD-1 monoclonal antibody." (PMID 41373645, 2025). "In mouse study, Pembrolizumab-IL-15Rα-IL-15 expressed acceptable tumor growth inhibition." (PMID 39808627, 2025). "Furthermore, fluorescent and light-sheet microscopy show that IL-15 complexes and anti-PD-1 mAb are present in the tumor-draining lymph node." (PMID 41373645, 2025). "Cytokines such as IL-2, IL-12, IL-15, and IL-18 enhance NK cells’ anti-tumor effects." (PMID 40260240, 2025). "By exploiting SCs' intrinsic tumor-tropic properties and engineering them to consistently express interleukin-15 (IL-15) via lipid nanoparticle-mediated mRNA transfection, the SC-NK cell complexes exhibit markedly improved tumor localization and sustained cytokine-mediated functional enhancement." (PMID 40827682, 2025). "Notably, B7-H6M4-LC21 combined with IL-15 fusion protein elicited synergistic tumor lysis (>90% at 10 ng/mL in vitro) and enhanced in vivo antitumor efficacy, surpassing T cell-based modalities." (PMID 40873574, 2025). "Antitumor effects have been demonstrated for fusion proteins composed of antibodies targeting different tumor-associated antigens (e.g., CEA, EDB, EDA, GD2, EGFR, FAP) and many cytokines of the common gamma chain receptor family (e.g., IL-2, IL-15, IL-15/IL15Rα, IL-21, IL-7)." (PMID 40370435, 2025). "Furthermore, the combination of CD25-targeted NIR-PIT and intraperitoneal injection of IL-15 induces an antitumor response in a tumor model." (PMID 41410776, 2025). "Moreover, microbiota-derived cyclic di-AMP can stimulate STING-mediated IFN-I production in monocytic cells, recruiting DCs and promoting IL-15-mediated NK cell activation within the tumor microenvironment." (PMID 41246357, 2025). "Additionally, the tumor microenvironment typically maintains insufficient concentrations of cytokines such as IL-15 that are necessary for the survival and optimal functioning of tumor-specific T-cells." (PMID 41154636, 2025).
tumor (continued). "These viruses exhibit tumor-selective replication and exert their effects through mechanisms such as direct oncolysis, the delivery of immunostimulatory genes (e.g., IL-12, IL-15, GM-CSF), the activation of innate and adaptive immune responses, and the remodeling of the tumor microenvironment." (PMID 40507337, 2025). "Recently, using a model involving transplantation and surgical resection of the murine MHC-I+Rae1b+ breast cancer line, EO771 showed that administering IL-15/IL-12-conditioned syngeneic NK cells following primary tumor removal enhanced the long-term survival of mice with minimal metastatic spread." (PMID 40410571, 2025). "In addition, IL-15 promotes apoptosis in immune cells and tumor cells and regulates the autophagic process, thereby affecting cell survival and function." (PMID 39958351, 2025). "Notably, the anti-PD-1-IL15 fusion showed improvement in anti-tumor activity and increased survival rates in mice compared to standalone Pembrolizumab treatment or co-treatment with IL-15-based molecule." (PMID 39808627, 2025). "Additionally, IL-15 signaling plays a crucial role in recruiting and activating NK cells within the tumor microenvironment." (PMID 40312353, 2025). "Prior studies have delivered an IL-15 superagonist intravenously or subcutaneously and have used dosing regimens in combination with PD-1/PD-L1; however, these studies have shown that increased survival and tumor immunity were short-lived." (PMID 41373645, 2025). "Similarly, complementary studies employing fluorescence-tracked IL-15/anti-PD-1 combinations have revealed dynamic spatiotemporal interactions between tumor microenvironments and secondary lymphoid organs, revealing mechanistic synergies in immunotherapy." (PMID 40746833, 2025). "Moreover, tumor-associated (MKI67) and CAF-related (FAP, Fibronectin, COL1A1) genes were downregulated in the FAP/IL-15 CAR-T group compared to other groups." (PMID 41455698, 2025). "Additionally, endogenous IL-15 secretion significantly enhances effector cell viability, enabling effective tumor suppression in mice through targeted elimination of CAFs in solid tumors." (PMID 41455698, 2025). "In line with this hypothesis, circulating PB-NK cells have been shown to acquire the tissue-residency markers CD49a and CD103 in vitro after 6 days of culture in the presence of IL-15 and tumor cell lines." (PMID 40607422, 2025). "Notably, exercise-induced interleukin-15 (IL-15) has emerged as a potential prognostic biomarker in this setting, with serum levels positively correlating with tumor inhibition." (PMID 40959054, 2025). "Building on our previous research, which demonstrated the efficacy of preconditioning CAR-T cells with IL-7/IL-15 to augment their anti-tumor capabilities, recent studies have shown promise in combining anti-PD-1 antibodies with CAR-T cell therapy for cancer treatment." (PMID 41450878, 2025). "IL-15 produced by MSLN.CAR-IL-15 iNK cells may also enhance the survival and functional capabilities of tumor-resident NK cells and CD8+ T cells." (PMID 40315330, 2025). "At 50 days following initial treatment, overall survival was significantly extended in mice that received IL-15 complex alone, anti-PD-1mAb alone, or the combined treatment of IL-15 complex plus anti-PD-1 compared to vehicle control mice (0/12 mice tumor-free)." (PMID 41373645, 2025). "In addition, we show colocalization of the IL-15 complex/anti-PD-1 within both the tumor-draining lymph node and the TME in the regressing tumor." (PMID 41373645, 2025). "Unlike interleukin-2 (IL-2), IL-15 avoids stimulating regulatory T cells (Tregs), which can suppress anti-tumor immunity, and is associated with lower toxicity and fewer side effects." (PMID 40520425, 2025). "They demonstrated that co-armoring with the pro-inflammatory cytokines IL-15 or IL-18 could overcome this limitation, resulting in significantly improved in vivo anti-tumor activity." (PMID 41019052, 2025).